SNORA63 (Small nucleolar RNA SNORA63 )
Synonyms: LOC124900196
Gene: Small nucleolar RNA gene on chromosome 5 (40,654,963 to 40,655,094, forward strand). Ensembl gene ENSG00000199552.
Gene Ontology:
Biological process: RNA processing
Cellular component: nucleolus
Homologues: Orthologues: macaque SNORA63 (96% identical), rabbit SNORA63 (85% identical), dog SNORA63 (80% identical), mouse Gm55296 (68% identical), chimpanzee SNORA63 (54% identical). Paralogues in human: SNORA63 (92% identical), SNORA63C (89% identical), SNORA63E (77% identical), SNORA63D (71% identical), SNORA63B (65% identical), SNORA63 (61% identical), SNORA63 (60% identical), SNORA63 (57% identical), SNORA63 (48% identical).
Diseases named in the same sentence as SNORA63 in open-access papers:
SNORA63 is named in the same sentence as 2 diseases in open-access papers, as found by Europe PMC text mining. Sharing a sentence is not in itself a finding about the gene and the disease.
SNORA63 shares sentences with these, for which no sentence is quoted: cancer (1 paper); mastitis (1).